PPP1R16A (protein phosphatase 1 regulatory subunit 16A)
Description:
Inhibits protein phosphatase 1 activity toward phosphorylase, myosin light chain and myosin substrates.
Synonyms: MYPT3; MGC14333
Tractability: Antibody: UniProt places it where antibodies can reach, with medium confidence; its Gene Ontology location is reachable by antibodies, with medium confidence; the Human Protein Atlas places it where antibodies can reach. PROTAC: ubiquitination databases record sites on it; its protein half-life has been measured.
Gene: Protein-coding gene on chromosome 8 (144,475,989 to 144,502,126, forward strand). Ensembl gene ENSG00000160972.
Subcellular location: Cell membrane
Subcellular location (Human Protein Atlas): Plasma membrane
Gene Ontology:
Molecular function: protein binding; enzyme inhibitor activity; myosin phosphatase regulator activity; protein phosphatase regulator activity
Cellular component: cytoplasm; plasma membrane
Genetic constraint (gnomAD): Loss-of-function variants: 37 observed, 38.02 expected, observed/expected ratio (o/e) 0.97, 90% interval 0.75 to 1.28. The synonymous counts are far from expectation, so gnomAD's model fits this gene poorly and the ratio says little. Missense variants: 766 observed, 637.59 expected, observed/expected ratio (o/e) 1.2, 90% interval 1.13 to 1.27. Synonymous variants: 394 observed, 278.33 expected, observed/expected ratio (o/e) 1.42, 90% interval 1.3 to 1.54.
Homologues: Orthologues: chimpanzee PPP1R16A (99% identical), rat Ppp1r16a (83% identical), mouse Ppp1r16a (82% identical), guinea pig PPP1R16A (72% identical), tropical clawed frog ppp1r16a (60% identical), zebrafish ppp1r16a (55% identical), Drosophila melanogaster MYPT-75D (41% identical), Caenorhabditis elegans gfi-2 (32% identical). Paralogues in human: PPP1R16B (49% identical).
Diseases named in the same sentence as PPP1R16A in open-access papers:
PPP1R16A is named in the same sentence as 6 diseases in open-access papers, as found by Europe PMC text mining. Sharing a sentence is not in itself a finding about the gene and the disease. The quoted sentences say what the papers report.
depression (1 paper, 2020). "Although many of the top genes do not have direct disease association, several have been linked to depression-like behavior in animal studies such as PPP1R16A and CASKIN1." (PMID 31165141, 2020).
liver cancer (1 paper, 2024). An epithelial or non-epithelial malignant neoplasm that arises from the liver. "Given that MIF acted as a macrophage stimulator, we speculate from cell communication results that PPP1R16A cells may promote macrophage aggregation through the MIF pathway, which inducing M2 polarization of liver cancer cells." (PMID 39010084, 2024).
ovarian carcinoma (1 paper, 2016). A malignant neoplasm originating from the surface ovarian epithelium. "The LY6H module is altered in 24% of ovarian cancer subtype 1 cases and includes three altered genes, namely, DVL3, LY6H, and PPP1R16A." (PMID 26735889, 2016).
ovarian clear cell adenocarcinoma (1 paper, 2023). A malignant glandular epithelial neoplasm characterized by the presence of clear and hobnail cells. "PPP1R16A, a protein coding gene, was reported to be associated with ovarian clear cell adenocarcinoma." (PMID 37189064, 2023).
tumor (2 papers, 2024). "Among them, the promoter methylation level of CLGN was stronger in the tumor group, while the methylation levels of the other three genes were significantly reduced in the tumor group, especially PPP1R16A." (PMID 39010084, 2024). "Single-cell analysis and cell communication indicated that PPP1R16A is predominantly distributed in liver malignant parenchymal cells and may reshape the tumor microenvironment by enhancing macrophage migration inhibitory factor (MIF)/CD74 + CXCR4 signaling pathways." (PMID 39010084, 2024). "Additionally, our experimental results suggest that knocking out PPP1R16A can inhibit the proliferation, invasion, and migration capabilities of HCC cells, indicating that PPP1R16A may be a crucial tumor-promoting factor." (PMID 39010084, 2024).
cancer (1 paper, 2021). A tumor composed of atypical neoplastic, often pleomorphic cells that invade other tissues. "As an example, we identified PPP1R16A as a CRC-specific gene with robust depletion of NDR cfDNA coverage in plasma samples from cancer patients as compared to healthy individuals, and GMFG as a blood-specific gene with greater coverage depletion in healthy blood plasma." (PMID 33850132, 2021).